MTDH (metadherin)
Diseases named in the same sentence as MTDH in open-access papers (continued):
Sharing a sentence is not in itself a finding about the gene and the disease.
tumor (continued). "In the present study, the inhibition of MTDH expression reduced tumor drug resistance in PC cells." (PMID 25684730, 2015). "All these results suggested that MTDH might function as a tumor growth promoter in HCC, meaning it potentially has great value in targeted therapy in HCC treatment." (PMID 26287185, 2015). "Furthermore, AEG-1/MTDH overexpression has been found to significantly correlate with tumor grade, clinical staging, T classification, metastasis classification and a shorter survival time, as determined by immunohistochemical analysis." (PMID 25009642, 2014). "The therapeutic targeting of AEG-1/MTDH may simultaneously block metastasis, suppress tumor growth and enhance the efficacy of chemotherapeutic treatments." (PMID 25009642, 2014). "Through a number of signaling cascades, AEG-1/MTDH is involved in several crucial aspects of tumor progression, including transformation, proliferation, the evasion of apoptosis, cell survival, migration and invasion, angiogenesis, metastasis and chemoresistance." (PMID 25009642, 2014). "However, in Iranian patients, AEG-1/MTDH mRNA expression was significantly elevated in 46.6% of examined tumor tissues, while its expression was low in others (36.6%)." (PMID 25009642, 2014). "In addition, compared to ECs isolated from normal liver tissues of HCC patients, ECs isolated from tumor tissues expressed markedly low levels of miR-302c but high levels of MTDH." (PMID 25027009, 2014). "Astrocyte elevated gene-1 [AEG-1; also known as Metadherin (MTDH) and Lysine-rich CEACAM1 co-isolated (LYRIC)] has emerged in recent years as a potentially crucial mediator of tumor malignancy, and a key converging point of a complex network of oncogenic signaling pathways." (PMID 25009642, 2014). "Immunohistochemical staining showed that FHIT expression was decreased in matched lymph node metastatic tissues compared to primary tumor tissue (9 of 40 cases), but MTDH and HMGA2 were significantly activated (11 of 40 and 10/40 cases, respectively) in the matched lymph nodes." (PMID 25340791, 2014). "Studies are ongoing to further clarify the biological impact of MTDH overexpression on DLBCL tumor cells, in which we investigated gain-of-function through MTDH upregulation induced by TNF-α and loss-of-function through MTDH knockdown by small interfering RNA in DLBCL cells." (PMID 22768080, 2012). "Recently, a number of studies have elucidated the multi-faceted role of MTDH in tumor progression." (PMID 21408129, 2011). "Notably, a study demonstrated that the overexpression of miR-375 in HNSCC cell lines, alongside MTDH knockdown, significantly reduced tumor formation in mice, underscoring the critical role of miR-375 in suppressing tumorigenic processes and its potential as a therapeutic target." (PMID 40076805, 2025). "We hypothesized that a reduction in MTDH would affect tumor development and progression." (PMID 36902125, 2023). "Moreover, the invasive and metastatic capabilities of tumor are also altered by MTDH." (PMID 36133745, 2022). "There is no significantly different TMB or neoantigen between low and high expressed MTDH patients, indicating that the mechanism of MTDH-associated immunotherapy resistance might be independent of tumor mutation burden and neoantigen numbers." (PMID 34622157, 2021). "Additionally, knockdown of MTDH inhibits the growth of xenograft tumor in vivo." (PMID 30227879, 2018). "In vivo results also showed that MTDH shRNA could effectively inhibit HepG2 tumor growth." (PMID 26287185, 2015). "Among them, EGFR(7p11.2), TWIST1(7p21.2), RAC1(7p22), MTDH(8q22.1), CCNE2(8q22.1), TNFRSF11B(8q24) and GRB2(17q25) might be good candidates, as they are reportedly associated with invasiveness and metastasis of tumor cells." (PMID 23457519, 2013).
tumor (continued). "The interaction between MTDH and SND1 is essential for the function of MTDH in tumor-initiating cells, suggesting their pivotal role in cancer progression and potential as therapeutic targets." (PMID 41286067, 2025). "In line with this notion, our results indicate that tumor cells utilize both the PI3K/AKT pathway and the E2F4-driven MTDH pathway to escape immunosurveillance." (PMID 41249116, 2025). "Conversely, in tumor cells with MTDH KD, the binding of SND1 to SESN2 was notably weakened, indicating the crucial role of MTDH in promoting the SND1-SESN2 interaction." (PMID 40775338, 2025). "Using narrow-down analysis, six tumor antigens (AGPS, NRAS, MTDH, PANX1, NOX4, and PPARD) were found to be related to better prognoses as well as the infiltration of antigen-presenting cells in LUAD." (PMID 38331967, 2024). "Considering the interaction between tumor antigens and APCs, these potential antigens were further screened through the TIMER database where it was found that AGPS, NRAS, MTDH, PANX1, NOX4, and PPARD genes were positively correlated with different APCs." (PMID 38331967, 2024). "The interaction of MTDH with IRE1α and its destabilization by VCP offers an interesting view on tumor control by functionally interacting MTDH, IRE1α, and VCP." (PMID 38727283, 2024). "Lastly, HIV-1 PR was shown to target Lyric (also named metadherin or AEG-1), a protein involved in several cellular pathways, such as NF-κB, Ras, Wnt, PI3K, tumor growth and metastatization." (PMID 36992421, 2023). "In a previous study, we demonstrated that MTDH is overexpressed in IBC cells and patient tumor tissues compared to normal tissues and in the tumor emboli." (PMID 36902125, 2023). "The tumor-suppressing actions of MSN and ENO1 were at least in part mediated by Metadherin (Mtdh), which is known to promote metastatic seeding." (PMID 36923539, 2023). "This study investigates the role of MTDH in IBC by assessing its function in cell proliferation, migration, tumor spheroid formation, signaling of oncogenic pathways, tumor progression, and metastasis." (PMID 36902125, 2023). "Given that our in vitro results suggested that MTDH knockout would decrease tumor growth, we developed IBC xenograft models using WT and MTDH knockout cells." (PMID 36902125, 2023). "Metadherin (MTDH) is expressed in a variety of malignancies, and treatment with Mtdh-ASO increases CD8+ T cells and enhances tumor immunity." (PMID 36569303, 2022). "The astrocyte elevated gene-1 (AEG-1), also known as metadherin (MTDH), is considered an oncogene whose overexpression contributes to carcinogenesis and tumor progression in various malignancies." (PMID 36362337, 2022). "Metadherin (MTDH), glutaminyl-peptide cyclotransferase (QPCT), topoisomerase II alpha (TOP2A), programmed death ligand 1 (PD-L1), and tumor-infiltrating lymphocytes (TILs) were evaluated in BC tissues pre-neoadjuvant for potential biomarkers." (PMID 35875123, 2022). "For instance, the MTDH gene known to be involved in the regulation of several signaling pathways—including Akt, Wnt, and MAPK, leading to tumor metastasis —was predicted to positively regulate the p27 pT198 (cyclin-dependent kinase inhibitor) level." (PMID 34010657, 2021). "Previous studies have shown that MTDH can activate several classic cancer-promoting signaling pathways, such as EMT, NF- κ B and MAPK to enhance tumor progression and metastasis." (PMID 35153736, 2021). "In this study, we aimed to investigate serum expression of miR-497 and metadherin in HCC patients (as noninvasive markers) and to evaluate their relationship to tumor characteristics and patients’ survival in order to assess their prognostic significance." (PMID 34577789, 2021).
tumor (continued). "In vitro overexpression of miR-375 reduces cellular proliferation and suppresses metadherin (MTDH), which functions to promote tumor invasion, metastasis, and chemoresistance." (PMID 32781574, 2020). "MTDH, also known as AEG1, is an oncogene that is considered to be an independent predictive factor for survival in various kinds of tumours." (PMID 32251289, 2020). "Hypoxia promotes cell invasion, tumor metastasis, and epithelial–mesenchymal transition by mediating the HIF-1α–MTDH loop in HNSCC cells." (PMID 33003428, 2020). "AEG-1, also known as metadherin (MTDH), and lysine-rich CEACAM1 co-isolate protein (LYRIC) greatly participate in carcinogenesis and tumor progression in several malignancies." (PMID 30833362, 2019). "We show that metadherin modulates alternative splicing via interactions with known splicing factors YTHDC1, Sam68 and T-STAR, potentially revealing novel tumour biomarkers and therapeutic targets." (PMID 31450747, 2019). "In this study, for tumor-specific MTDH knockdown, we constructed an amphiphilic PLGA-based copolymer NP for co-delivery of anti-MTDH siRNA and TAX into tumors." (PMID 30227879, 2018). "Hsa-miR-542-3p acts as tumor suppressor by targeting survivin (BIRC5), the oncogene astrocyte-elevated gene-1 (MTDH), or angiopoietin-2 (ANGPT2) that plays a role in tumor angiogenesis." (PMID 29293623, 2018). "AEG-1 (also known as metadherin, MTDH, or lysine-rich CEACAM1 co-isolated, LYRIC) has emerged in recent years as a potentially crucial mediator of tumor malignancy and a key converging point of a complex network of oncogenic signaling pathways." (PMID 28977913, 2017). "Microscopic examination of the tumor sections and quantitative evaluation of apoptosis by density mean and IOD shows that compared with the untreated controls, AED-1/MTDH siRNA-treatment increased the number of TUNEL-positive cells." (PMID 26909607, 2016). "AEG-1, also known as metadherin(MTDH) or lyric, plays a functional role in all important hallmarks of an aggressive tumor, including transformation, invasion, metastasis, angiogenesis, evasion of apoptosis and chemoresistance." (PMID 25987128, 2015). "In the present study, we aimed to examine the effects of MTDH silencing on HCC cell viability in vitro and tumor growth in vivo." (PMID 26287185, 2015). "In conclusion, we found that MTDH high expression in HCC tissues and higher MTDH protein levels are found in most HCC cancerous tissues compared with their matched adjacent non-tumor tissues." (PMID 26287185, 2015). "SYBR green-based qRT-PCR assays were carried out to detect the expression level of MTDH in 12 HCC tissues and matched adjacent non-tumor tissues." (PMID 26287185, 2015). "The inhibition of AEG-1/MTDH in neoadjuvant or adjuvant settings not only increases the response rate of chemotherapy, but also reduces tumor growth and the systemic spread of metastatic cancer." (PMID 25009642, 2014). "In conclusion, the AEG-1/MTDH protein is overexpressed in RCC and is important in tumor differentiation and progression." (PMID 25009642, 2014). "Stabilizing the feedback of HIF-1α and MTDH, and activating PI3K would form a positive feedback loop to enhance tumor cells’ survive and the progression." (PMID 23984913, 2013). "Metadherin plays an important role in inducing epithelial-mesenchymal transformation (EMT), proliferation, and invasion of tumor cells, promoting treatment resistance and mesenchymal hypercytosis while increasing the vulnerability of tumor cells to ferroptosis inducers, especially GPX-4 inhibitors." (PMID 40169575, 2025). "Additionally, an early report indicates that MTDH S-palmitoylation suppresses its interaction with SND1, thereby inhibiting tumor growth of HCC." (PMID 41318030, 2025). "More studies could be conducted to better understand the relationship between MTDH depletion and E-cadherin function in IBC since MTDH was also found present in tumor emboli in our previous studies." (PMID 36902125, 2023).
tumor (continued). "A reduction in tumor size was observed at weeks 1 and 2 in sg-MTDH tumors compared to WT, and, contrary to what we expected, the absence of MTDH did not reduce tumor volume or tumor weight." (PMID 36902125, 2023). "Based on these findings, we propose that a lack of MTDH delays the proliferative capacity of tumor initiating cells, which affects the initial stage of tumor development and does not affect primary tumor growth but regulates invasion and metastasis." (PMID 36902125, 2023). "Therefore, our results suggest a functional role for MTDH in the aggressiveness of IBC by affecting cell proliferation, tumor spheroid formation, migration, and invasion." (PMID 36902125, 2023). "We previously reported that MTDH is overexpressed in the plasma membrane of IBC cells compared to non-cancerous mammary cells and nIBC cell lines, in addition to its presence in IBC tissues and the tumor emboli." (PMID 36902125, 2023). "In addition, Metadherin on cancer cell surface communicated with CEACAM1 on macrophages to secrete C–C motif chemokine ligand 3 (CCL3), which promotes various tumor types of metastasis." (PMID 36497444, 2022). "Indeed, binding of MTDH and SND1 stimulates the RISC activity and consequently facilitates the gene silencing of tumor suppressor mRNAs via either small interfering RNA (siRNA) or microRNA (miRNA) processes." (PMID 33802672, 2021). "As expected, gene products in terms related to tumor progression such as positive regulation of angiogenesis were dysregulated in the absence of MTDH." (PMID 33802672, 2021). "Our study showed that the most differential genes in the high expression of MTDH tumor might be enriched in the activation of the PI3K/Akt pathway, indicating MTDH may regulate PI3K/Akt-induced EMT by m6A RNA methylation." (PMID 34622157, 2021). "As the results showed, peritumoral injection of liposome-encapsulated miR-26a-5p-inhibitor promoted subcutaneous tumor growth about 50% under treatment of PTX (p < 0.001), and down-regulation of MTDH increased the PTX-induced tumor growth inhibition about 30% (p < 0.001)." (PMID 34740994, 2021). "The nuclear localization of MTDH protein has three putative, lysine-rich NLS sequences in the prostate tissue that might result from RNA splicing in different tumor types." (PMID 33003428, 2020). "MTDH is upregulated in multiple cancer tissues and cell lines, induce EMT via oncogenic signaling pathways including PI3 K/Akt, ERK, Wnt/β-catenin signaling, thus enhance tumor metastasis." (PMID 30065618, 2018). "Moreover, the luciferase assay confirmed that miR-145 and miR-497 attenuated MTDH expression by directly binding 3′-UTR of MTDH mRNA and exert the tumor-suppression role." (PMID 30065618, 2018). "The expression of MTDH are presented at a higher levels in TLR4 positive breast cancer cells (MDA-MB-231,MCF-7,and MDA-MB-468) than that in TLR4 negative T47D cell lines after treated with LPS, suggesting the pro-tumor role of TLR4 expressed on tumor cells." (PMID 29029545, 2017). "MTDH has been shown to induce EMT in several tumors and promote tumor invasion." (PMID 28107197, 2017). "In 2002 and 2004, several groups, under different experimental settings, reported identification of the gene, first named as astrocyte elevated gene 1 (AEG-1), now having the GenBank symbol as MTDH, which stands for metadherin, for its involvement in tumor metastasis and adhesion." (PMID 22060137, 2011). "Targeting PI3K/AKT may not be sufficient, as tumor cells can exploit E2F4/MTDH to develop resistance." (PMID 41249116, 2025). "However, the biochemical and molecular mechanisms of Metadherin, and the relationship between Metadherin expression and tumor immune cell infiltration in BC are still not very clear." (PMID 38253625, 2024).
tumor (continued). "Furthermore, because our group and others have demonstrated the importance of the JAK2/STAT3 pathway in the regulation of IBC cellular identity, stemness, and tumor progression, herein, we also investigated the modulation of STAT3 expression after MTDH knockout." (PMID 36902125, 2023). "In this study, we were not able to clarify the tumour-promoting mechanism of MTDH." (PMID 32251289, 2020). "Nevertheless, the free siRNA does not decrease the MTDH expression in tumor tissues." (PMID 30227879, 2018). "Our results demonstrate that the absence of MTDH significantly reduces IBC cell migration, proliferation, tumor spheroid formation, and the expression of NF-κB and STAT3 signaling molecules, which are crucial oncogenic pathways in IBC." (PMID 36902125, 2023). "Our findings show that the absence of MTDH significantly decreases IBC cell proliferation, migration, invasion, and tumor spheroid formation and decreases the expression of various signaling molecules." (PMID 36902125, 2023).